RNU6-1189P (RNA, U6 small nuclear 1189, pseudogene)
Gene: Small nuclear RNA gene on chromosome X (47,087,506 to 47,087,612, forward strand). Ensembl gene ENSG00000206685.
Homologues: Orthologues: chimpanzee U6 (98% identical), macaque U6 (93% identical), dog U6 (80% identical). Paralogues in human: RNU6-25P (91% identical), RNU6-33P (91% identical), RNU6-38P (91% identical), RNU6-698P (91% identical), RNU6-891P (91% identical), RNU6-1 (90% identical), RNU6-2 (90% identical), RNU6-20P (90% identical), RNU6-3P (90% identical), RNU6-48P (90% identical), RNU6-4P (90% identical), RNU6-5P (90% identical), and 1287 more.